CLDN6 (claudin 6)
Diseases named in the same sentence as CLDN6 in open-access papers (continued):
Sharing a sentence is not in itself a finding about the gene and the disease.
cancer (continued). "More recently, there have been several studies evaluating claudin-6 (CLDN-6), a tight junction protein, which is abnormally expressed in several cancers, as a potential therapeutic target." (PMID 39766027, 2024). "Only a fraction of NK-92MI and CD19-CAR NK cells exerted cytotoxicity, while the majority of CLDN6-CAR NK cells contacting cancer cells showed obvious killing behavior, with thin lamellar protrusions and filar structures formed in the cell front." (PMID 38481806, 2024). "In conclusion, our results clarified the role of CLDN6 in the relationship between cell homeostasis and cancer metastasis, and revealed the molecular mechanisms." (PMID 36935496, 2023). "RNA-Seq data from 89 EACs and 371 GACs were obtained from The Cancer Genome Atlas project and EAC/GAC cases were stratified by CLDN6 mRNA expression based on a survival-associated cutoff." (PMID 37592303, 2023). "High and frequent CLDN6 expression is found in germ cell tumors, epithelial ovarian cancer, endometrial carcinoma, and various other cancer types, including rare malignancies." (PMID 37592303, 2023). "For example, CLDN4 overexpression, an indicator of poor clinical outcome in patients with ovarian cancer, is an indicator of resistance to cisplatin in this cancer type, and a similar role for CLDN6 is seen in cervical adenocarcinoma." (PMID 38137355, 2023). "Obviously, the cell phase arrested by the variety of CLDN6 levels was distinct in different kinds of cancer." (PMID 36362009, 2022). "In summary, CLDN6 possesses pro- or anti-cancer effects in different cancers through its regulation of cell proliferation and apoptosis via different pathways." (PMID 36362009, 2022). "The COX proportional hazard model of cancer progression suggested that, in addition to age, histological grade, and lymph node status, the change in ER and CLDN6 expression had a significant effect on cancer progression." (PMID 35847894, 2022). "Although CLDN6 takes part in cell apoptosis and proliferation in cancers, its regulatory role in bovine CCs is unclear." (PMID 36362009, 2022). "There were significant differences in age, histological grade, number of positive nodes, and changes of ER and CLDN6 in cancer progression (all p < 0.05)." (PMID 35847894, 2022). "Recently, the role of CLDN6 in cancer has attracted extensive attention from researchers as an ideal therapeutic target." (PMID 36362009, 2022). "Taken together, CLDN6 is a potential biomarker for diagnosis and prognosis in pan-cancer and a promising molecular target for UCEC." (PMID 34409042, 2021). "CLDN6 is an ideal target for antibody approaches of high potency in cancers with high CLDN6 expression based on the fact that CLDN6 is undetectable in the adult tissues." (PMID 35008557, 2021). "As a result, CLDN6 expression differs significantly not only in most cancers but also in different molecular and immune subtypes of cancers." (PMID 34409042, 2021). "CLDN6 expression is aberrantly activated in various cancer types such as mentioned in Section 5.1, so CLDN6 is an ideal target for antibody approaches of high potency." (PMID 34948213, 2021). "The roles of CLDN6 in cancers cannot be explained by the barrier function, and they appear to be mediated by key signaling pathways." (PMID 34948213, 2021). "It is worth pointing out that CLDN6 is closely correlated with both molecular subtype and immune subtype in six types of cancers, including UCEC, BRCA, STAD, OV, LUSC, and HNSC." (PMID 34409042, 2021). "CLDN6 is studied to be used for emerging immunotherapies to treat cancers including monoclonal antibodies, bispecific antibodies (BsAbs), antibody–drug conjugates (ADCs), and chimeric antigen receptor (CAR) T-cell therapy." (PMID 34948213, 2021). "Meanwhile, we observed that CLDN6 was significantly correlated with different immune subtypes in nine cancer types." (PMID 34409042, 2021).
cancer (continued). "In summary, CLDN6 is involved in the regulation of cancer cell proliferation and apoptosis through different pathways, which results in pro- or anti-cancer effects of CLDN6 in different cancers." (PMID 34948213, 2021). "Bioinformatic analysis has revealed that CLDN6 is regulated by a diverse set of transcription factors and promotes cancer cell behavior via the ASK1-p38/JNK MAPK secretory signaling pathway." (PMID 34249076, 2021). "CLDN6 has a potential role in the diagnosis and prognosis of cancers involving deregulated HIF-1α, and subsequently HIF-1α/SENP1-blocked therapies." (PMID 32093760, 2020). "The oncofetal tight junction molecule Claudin 6 (CLND6) constitutes such a TAA for anti-cancer immunotherapy." (PMID 29203786, 2017). "We have found claudin-6 was a anti-cancer gene in claudins family, and the up-regulation of claudin-6 has important clinical implication, but details of the mechanism was not clear." (PMID 22925655, 2012). "Similarly, CLDN6 has garnered attention as a potential therapeutic target, particularly in adult cancers characterized by its overexpression." (PMID 38731853, 2024). "Indeed, in vitro cell viability analyses performed on cancer cells post-treatment demonstrated that CLDN6-23-ADC was at least 10-fold more potent than CLDN6-23-mAb." (PMID 38371623, 2024). "Altogether, a single-cell level cytotoxicity assay based on live cell imaging revealed that the powerful CAR1-NK cells targeting CLDN6 constructed by self-active elements significantly enhanced the specifical killing efficacy against CLDN6-positive cancer cells." (PMID 38481806, 2024). "Likewise, CLDN6 has become an interesting target for cancer therapy, and CLDN-6-targeting chimeric antigen receptor (CAR)-T cell therapy has shown positive outcomes in vitro and in mice models." (PMID 38731853, 2024). "Claudin-6 recently gained attention as a novel target for CAR-T cell cancer therapy." (PMID 38338705, 2024). "Moreover, CLDN7 and CLDN11 play cancer-promoting roles in the pathogenesis of CRC, whereas CLDN6 plays a cancer-promoting role in the pathogenesis of GC." (PMID 38201579, 2023). "Additionally, we observed significant expression of CLDN6, CES1, SOST, SPRR2A, MYBPH, CGB5, and KRT1 in the high-risk group, suggesting their potential involvement as cancer-promoting genes in BLCA development." (PMID 37780567, 2023). "CLDN6 expression levels are altered in various types of cancer." (PMID 36620607, 2022). "More importantly, many genes were affected, and the significant up-regulation of ABAT and CLDN6 genes might inhibit the cancer cells proliferation and induce cell apoptosis." (PMID 35659243, 2022). "Furthermore, CLDN6 was used as a surface marker of mouse pluripotent stem cells and an ideal therapeutic target in cancer." (PMID 36362009, 2022). "In summary, there is controversy in the different expression levels of CLDN6 in different cancers." (PMID 36362009, 2022). "More importantly, NAC induces cancer cycling hypoxia which might be related to the phenotypic drift of cancer; the decrease in ER and CLDN6 could clearly indicate bad prognosis." (PMID 35847894, 2022). "Claudin-6 (CLDN6) is one of the 27 family members of claudins and majorly involved in the tight junction and cell-to-cell adhesion of epithelial cell sheets, playing a significant role in cancer initiation and progression." (PMID 34409042, 2021). "However, there is no existing study to our knowledge to evaluate the significance of CLDN6 in pan-cancer on the whole scale." (PMID 34409042, 2021). "The discrepancies between the dual roles of CLDN6 in human cancers may be due to the heterogeneity and complexity of tumors." (PMID 34409042, 2021). "Importantly, the roles of CLDN6 in cancers have gained focus and are being investigated in recent years." (PMID 34948213, 2021).
cancer (continued). "In terms of its various characters in human cancers, CLDN6 may be a helpful positive marker for further identification of atypical teratoid/rhabdoid tumors (AT/RTs) for diagnosis and therapy." (PMID 34409042, 2021). "The results showed that CLDN6 and β-catenin directly interacted in the cytoplasm of cancer cells." (PMID 32093760, 2020). "Being virtually absent from any normal tissue due to transcriptional silencing in adult healthy tissues CLDN6 is aberrantly and frequently expressed in various types of cancers of high medical need such as ovarian, lung, gastric breast, prostate, and pediatric cancers." (PMID 29203786, 2017). "It remains notable however that compensatory junctional components may be up-regulated by Cldn6 TG mice during the abrogation of SHS-induced inflammation that may culminate in remodeling or cancer progression." (PMID 27763528, 2016). "In addition, it is reported that CLDN6 expression is regulated by DNA methylation in various human cancers and cell lines." (PMID 27461117, 2016). "However, claudin-6 expression has been reported in multiple human cancers such as rhabdoid tumors, breast cancers and gastric cancers." (PMID 23685873, 2013). "Additionally, it would be valuable to investigate whether other stimuli, such as hypoxia and starvation, also affect the ROS/GATA4/CLDN6 axis and whether there are variations in the response across various cancer cell types." (PMID 40959289, 2025). "Cancer cells undergoing the EMT process through overactivation of TGFβ signaling exhibit sustained hypermethylation of promoters and subsequent loss of expression in downstream cell-junction-related effector genes, including cadherin 1 (CDH1) and claudin 6 (CLDN6)." (PMID 37566041, 2023). "However, as the previous studies reported, CLDN6 may take diverse parts in different cancers, even in different subtypes of the same cancer, either for cancer promotion or for cancer suppression." (PMID 34409042, 2021). "Finally, we focused on the emerging roles of CLDN6 in cancers." (PMID 34948213, 2021). "Hence, the research focused on a distinct molecular subtype or immune subtype of cancers may provide an appropriate entry point to explore the role of CLDN6." (PMID 34409042, 2021). "We believe that CLDN6 may inhibit migration and invasion of cancer cells via EMT suppression." (PMID 28867761, 2017). "A phase I clinical trial of ixotatug vedotin for the treatment of advanced cancers (NCT05103683) revealed favorable safety profiles and preliminary efficacy across CLDN6-positive ovarian, endometrial and testicular cancer patients." (PMID 41164107, 2025). "These preliminary results suggest that CLDN6 CAR-T cell therapy combination with CAR-Vac, is not only safe but also holds considerable therapeutic promise for patients with CLDN6-positive cancers." (PMID 41024300, 2025). "Claudin family genes (e.g., CLDN6, CLDN19) are also served as biomarkers and therapeutic targets across cancers." (PMID 41287033, 2025). "The CLDN6 gene acted as the oncogene in HCC and enhanced cancer cell invasion, migration, and proliferation through EGFR/AKT/mTOR signaling pathway." (PMID 35150083, 2022). "Thus, downregulation of CLDN6 could lead to a different invasive phenotype in cancer cells." (PMID 34405008, 2021). "CLDN6 is a target for CPE, which made a possibility for it to act as a targeted therapy for cancers that expressed CLDN6." (PMID 34948213, 2021). "However, the biological significance of CLDN6 expression in these cancers remains unclear." (PMID 32987797, 2020). "Thus, downregulation of CLDN6 could lead to a more invasive phenotype in cancer cells." (PMID 28867761, 2017).
cancer (continued). "The unique cancer-selective expression of CLDN6 (absent in normal uterus) makes it an ideal ADC target, and early phase trials are underway." (PMID 40687428, 2025). "Despite having almost no expression in normal adult tissue, CLDN6 is expressed at elevated levels in multiple human cancers including ovarian and endometrial malignancies." (PMID 38731853, 2024). "In addition, exogenous CLDN6 expression in HCC cell lines resulted in increased colony formation and cancer cell proliferation." (PMID 38371623, 2024). "Claudin 6 (CLDN6) is an oncofetal antigen that is largely absent in healthy tissues and upregulated in several cancers, making it a promising therapeutical target." (PMID 37592303, 2023). "In addition to traditional functions of CLDN6 in permeability regulation and barrier formation, CLDN6 connects proteins containing PDZ domain or PBM through its PBM, regulating intracellular signaling pathways to affect the malignant phenotype of cancer." (PMID 36935496, 2023). "Previous studies found that CLDN6 was not expressed in healthy adult tissues but was expressed in various cancers and many types of embryonic epithelia." (PMID 36362009, 2022). "We explored the correlations between CLDN6 differential expression and molecular subtypes in pan-cancer from the TISIDB database and found that CLDN6 was expressed differently in different molecular subtypes of seven cancer types, including UCEC, BRCA, ESCA, LUSC, HNSC, OV, and STAD." (PMID 34409042, 2021). "In earlier studies, we found that CLDN6 overexpression inhibited the migration and invasion of MCF-7 cells in vitro, while the expression of CLDN6 was undetectable or low in several human cancer cells." (PMID 28867761, 2017). "Because Cldn6, even in the TG animal, is inhibited by SHS, much more research is needed that exhaustively considers other tight junctional components and how they participate during inflammation and cancer." (PMID 27763528, 2016). "Moreover, hypermethylation of CLDN6, CLND7 and CLDN15 have also been observed in different cancer entities." (PMID 26198249, 2015). "Based on this work, we initiated a phase 1/2 first-in-human clinical trial to evaluate CLDN6 CAR-T cells alone and in combination with CARVac in patients with relapsed or refractory (r/r) CLDN6-positive solid tumors in a dose escalation part followed by cancer type-specific dose expansion cohorts." (PMID 37872225, 2023). "In our present study, the oxygen concentrations of cancer tissues with LABC were monitored during NAC; the expressions of ER and CLDN6 before and after NAC were detected; and the relationship between the NAC response and the expressions of ER and CLDN6 was analyzed." (PMID 35847894, 2022). "A promising area of research involves XmAb541 and CTIM-76, bsAbs targeting claudin-6 (CLDN6), a tight junction protein that is selectively expressed on cancer cells with little to no presence in normal healthy tissue." (PMID 41211166, 2025). "The oncofetal protein Claudin 6 (CLDN6), virtually absent in normal body tissues, is aberrantly—but frequently—expressed in various cancer entities and therefore targeted by CAR-approaches." (PMID 36077730, 2022). "However, in triple-negative breast cancer cells MDA-MB-231, GSTP1 is lost, CLDN6 enhances chemoresistance to ADM via activating the AF-6/ERK signaling pathway and up-regulating cancer stem cell characters." (PMID 34948213, 2021).
infection (8 papers, 2009 to 2023). The state of being infected such as from the introduction of a foreign agent such as serum, vaccine, antigenic substance or organism. "Consistently, the treatment of S7-A cells with anti-CLDN6 antibodies resulted in more than 80% inhibition of infection with HCV-JFH1-based HCVpp with M706L mutation." (PMID 36424447, 2022). "Indeed, infection with HCV-JFH1-based HCVpp having M706L mutation was prevented by more than 75% when CLDN6 was knocked down in S7-A cells by two types of CLDN6 siRNAs." (PMID 36424447, 2022). "Furthermore, infection of 253G1 cells with HCV-JFH1-tau Lot B1 having M706L mutation was blocked by anti-CLDN6 antibody as well as anti-CD81 and anti-OCLN antibodies." (PMID 36424447, 2022). "HCV H77pp infection of CLDN6- and CLDN9-transduced HEK293T cells confirmed that the ectopic protein was correctly folded and functional." (PMID 37310242, 2023). "LDN1/CLDN6 double-knockout Huh-7.5 cells support infection by a mutant HCV only when CLDN1, CLDN6, or CLDN9 is expressed." (PMID 38203503, 2023). "We further tested the effects of M706L mutation on CLDN6 usage in various HCV strains (J6 (genotype 2a), H77 (genotype 1a), TH (genotype 1b)) as well as HCV-JFH1 (genotype 2a) using pseudoptype HCV infection system." (PMID 36424447, 2022). "The expression of claudin-6 and -9 in 293T cells resulted in the cells becoming permissive to HCVpp infection at similar levels as Huh7.5 and permissive to HCVcc infection, but at titers 400 times lower than those achieved in Huh7.5 cells." (PMID 19643019, 2009). "Thus, CLDN6 is more likely than CLDN9 to contribute to M706L-carrying HCV-JFH1 infection in hepatic Huh7-derived cells." (PMID 36424447, 2022). "CLDN1, CLDN6, and CLDN9 usages on HCVpp infection were previously reported in other genotypes than genotype 2a, which HCV-JFH1 belongs to22,23." (PMID 36424447, 2022). "Whereas HCV-JFH1-tau infection depends only on CLDN1, HCV-JFH1-tau/M706L infection exhibited the expanded receptor usage options: CLDN1, CLDN6, and CLDN9 proteins." (PMID 36424447, 2022). "Cldn1-specific neutralizing antibodies only partially inhibited infection of Huh7.5 cells by HCV strains with broad claudin tropisms, suggesting a possible escape from Cldn1-specific targeting molecules through Cldn6 or Cldn9 in cell culture." (PMID 31561440, 2019). "When S7-A cells were infected with HCV-JFH1-tau Lot B1 with or without a broad CLDN binder, i.e., C-terminal fragment of Clostridium perfringens enterotoxin (C-CPE), which can bind several CLDNs such as CLDN3, CLDN6, CLDN7, and CLDN917,18, infection was completely blocked by C-CPE." (PMID 36424447, 2022). "Taken together, the data indicate that high affinity cCPE-SSS binding to Cldn1 is efficiently inhibiting HCV infection of Huh7.5 cells whereas high affinity cCPEwt binding to Cldn6 is not sufficient to inhibit the infection efficiently." (PMID 31561440, 2019). "CCl-LP-1 cells do not express detectable levels of claudin-6 or -9 mRNA suggesting that infection is claudin-independent." (PMID 25701818, 2015). "Furthermore the expression of claudin-6 and -9 in claudin-1 negative hepatoma cell lines was not effective in conferring the ability to become HCVpp permissive, but the expression of claudin-1 made the cell line permissive to HCVpp infection." (PMID 19643019, 2009).
Blood Cancer (1 paper, 2025). "Interestingly, a high expression of CLDN6 was also seen in some samples of rare blood cancer subtypes, including a core-binding factor AML." (PMID 40149257, 2025).
CLDN6 also shares sentences with these, for which no sentence is quoted: bladder urothelial carcinoma (2 papers); breast (2); Ewing sarcoma (2); glioblastoma (2); hepatoblastoma (2); osteosarcoma (2); prostate carcinoma (2); renal carcinoma (2); acute megakaryoblastic leukemia (1); adenocarcinoma (1); brain tumors (1); breast fibroadenoma (1); carcinosarcoma (1); cervical squamous cell carcinoma (1); cholangiocarcinoma (1); colon adenocarcinoma (1); Colorectal tumors (1); delirium (1); diabetes (1); digestive system tumors (1); E. coli infection (1); embryonal tumors (1); endocervical adenocarcinoma (1); esophageal adenocarcinoma (1); gynecologic cancers (1); head and neck squamous cell carcinoma (1); hematological cancers (1); Hyperkeratosis (1); hypopharyngeal squamous cell carcinoma (1); Luminal A (1).
A further 23 diseases each share a sentence with CLDN6 in 1 paper.